SPOP (speckle type BTB/POZ protein)
Diseases named in the same sentence as SPOP in open-access papers (continued):
Sharing a sentence is not in itself a finding about the gene and the disease.
prostate carcinoma (continued). "We hypothesized that some prostate cancer-associated mutations in SPOP might disrupt the interaction between wild-type SPOP and ATF2." (PMID 29996942, 2018). "This tumor suppressor effect is abrogated by prostate cancer associated SPOP mutations." (PMID 30607139, 2018). "In addition, HDAC inhibition decreases AR full‐length and splice variant mRNA levels in the PTEN loss and SPOP mutant prostate cancer models." (PMID 29572264, 2018). "Notably, SPOP, a relatively new gene regulating DNA damage repair, is the most frequently mutated gene in prostate carcinoma." (PMID 29986747, 2018). "Notably, ectopic expression of F133V (a hotspot mutation of SPOP) in human prostate cancer cells or knock‐in of this mutant in the mouse prostate results in an abnormal activation of AKT‐mTORC1 signaling." (PMID 29523594, 2018). "TRIM24 is stabilized in SPOP-mutated prostate cancers, but the regulation of TRIM24 in wild-type prostate cancers is unknown." (PMID 30479348, 2018). "Notably, the most frequently mutated gene in prostate cancer is SPOP (speckle-type POZ protein), which encodes a substrate adaptor for the Cullin3 E3 ubiquitin ligase complex, with recurrent mutation in up to 15% of prostate cancers." (PMID 29996942, 2018). "Notably, all the SPOP mutations found in prostate cancers exclusively occur in the MATH domain, which is responsible for substrate binding." (PMID 29996942, 2018). "To test this hypothesis, we generated a series of Myc-tagged prostate cancer-associated mutants of SPOP, including Y87C, Y87N, F102C, S119 N, F125 V, K129E, W131G, W131C, F133 L, F133 V and K134 N, and examined their capacity to promote ATF2 degradation." (PMID 29996942, 2018). "Thus, our data suggest that inhibition of HDAC3 effectively suppresses the growth of SPOP‐mutated prostate cancer cells by shutting down both AKT and AR signaling pathways." (PMID 29523594, 2018). "Approximately 10% of prostate cancer patients harbor SPOP mutations." (PMID 29523594, 2018). "Thus, it is important to identify a common target to inhibit both AKT‐mTORC1 and AR signaling in SPOP‐mutated prostate cancer." (PMID 29523594, 2018). "A previous study showed that SPOP was mutated up to 15% of patients with prostate cancer." (PMID 29996942, 2018). "The SPOP mutation is the most common point mutation (6%–15%) in all prostatic cancers." (PMID 29581876, 2018). "Thirdly, SPOP is the most frequently mutated gene in primary prostate cancer." (PMID 29523594, 2018). "The gene encoding SPOP is the most frequently mutated gene in human primary prostate cancers." (PMID 29523594, 2018). "Additionally, SPOP, an E3 ligase substrate binding protein frequently mutated in prostate cancer, was also reported to target BET proteins for ubiquitination-mediated degradation." (PMID 29888169, 2018). "One of the conclusions of these studies is that mutual exclusivity between SPOP mutation and ERG rearrangement is due to functional redundancy, and that ERG stabilization is a critical downstream mediator of the oncogenic effects of SPOP mutation in prostate cancer." (PMID 29202479, 2018). "This study suggests that a polymorphism at 7p14.3 may predispose to SPOP mutant prostate cancer subclass through a hormone-dependent DNA damage response." (PMID 28663546, 2017). "Moreover, in vivo ubiquitination assay indicated that prostate cancer-associated SPOP mutants largely lost the capacity to promote INF2 polyubiquitination." (PMID 28448495, 2017). "Interestingly, most SPOP mutations identified in human prostate cancers, such as Y87C, F102C, W131G, and F133L, are located in the MATH domain of SPOP, which presumably impairs its ability to bind to and recruit substrates into the Cullin 3SPOP complex." (PMID 28599312, 2017).
prostate carcinoma (continued). "In summary, PRISM-SRM provides a sensitive, isoform-specific, multiplexed, and antibody-independent approach for quantification of SPOP mutations at the protein level, which holds great promise for the verification of the mutant SPOP proteins as biomarkers for prostate cancer." (PMID 28810879, 2017). "Moreover, prostate cancer-associated SPOP mutants increase INF2 localization in ER and promote mitochondrial fission, probably through a dominant-negative effect to inhibit endogenous SPOP." (PMID 28448495, 2017). "The qualitative and quantitative study of mutant SPOP proteins can contribute to improved understanding of the functional significance and molecular mechanism of SPOP mutations in prostate cancer, and their relevance for targeted cancer therapies in clinical applications." (PMID 28810879, 2017). "We postulated that prostate cancer-associated mutants of SPOP may be defective in mediating INF2 polyubiquitination." (PMID 28448495, 2017). "Considering INF2 is an important regulator of actin polymerization and mitochondrial fission, we explored whether INF2 is an authentic SPOP substrate and its function is dysregulated in SPOP-mutated prostate cancer." (PMID 28448495, 2017). "Interestingly, the SPOPF133V mutation is the most frequently mutated residue in prostate cancer (~50% of the total SPOP mutations)." (PMID 28810879, 2017). "SPOP mutations have been found in TCGA prostate cancer (10.2%), but with ∼70% has altered either Tryptophan residue at 131 position or Phenylalanine residue at 133 position, while mutations of ZNF148 and EZH1 were commonly observed in melanoma as well with no hot mutation spot." (PMID 28580939, 2017). "Taken together, our findings suggest that INF2 ubiquitination may be dysregulated by oncogenic prostate cancer-associated SPOP mutants." (PMID 28448495, 2017). "Moreover, three prostate cancer-associated SPOP mutants (Y87N, F125V and F133L) nearly lost their cytoplasmic localization compared with wild-type SPOP." (PMID 28448495, 2017). "We hypothesized that prostate cancer-associated mutations of SPOP might disrupt the interaction between wild-type SPOP and INF2." (PMID 28448495, 2017). "Thus, our results provide a functional link between SPOP mutations and dysregulation of mitochondrial dynamics in prostate cancer." (PMID 28448495, 2017). "SPOP gene was frequently altered by somatic point mutations in a distinct molecular subclass of prostate cancer, although the precise role that SPOP mutation plays in the development of prostate cancer is unclear." (PMID 28448495, 2017). "Prostate cancer is a heterogeneous disease, and many cases show somatic mutations of SPOP." (PMID 28663546, 2017). "Here, the authors show that a non-coding polymorphic regulatory element at 7p14.3 may predispose to SPOP mutant prostate cancer subclass through a hormone dependent DNA damage response." (PMID 28663546, 2017). "Moreover, SPOP mutations fail to mediate CHOP degradation and suppress CHOP-induced apoptosis, which indicates CHOP involvement in the progression of prostate cancer is associated with SPOP mutations." (PMID 29230213, 2017). "Importantly, prostate cancer-associated SPOP mutants fail to induce ERG degradation, whereas the majority of TMPRSS2-ERG fusions encoding N-terminal truncated ERG proteins are resistant to SPOP-mediated degradation." (PMID 27200299, 2016). "Again, prostate cancer-associated SPOP mutants cannot target SRC-3 for degradation." (PMID 27200299, 2016). "Furthermore, co-immunoprecipitation assays showed that endogenous ERG associates with speckle-type POZ protein (SPOP) ubiquitin ligase in LNCaP prostate cancer cells (see also Section 7)." (PMID 27208692, 2016). "SPOP mutations occur early in the history of prostate cancer, based on clonality analysis reported here and presence in the prostate cancer precursor high grade prostatic intraepithelial neoplasia (HG-PIN), potentially consistent with a ‘gatekeeper’ role in genome maintenance." (PMID 26374986, 2015).
prostate carcinoma (continued). "SPOP mutations are the most common point mutations in prostate cancer, but their role in promoting prostate cancer pathogenesis remains unclear." (PMID 26374986, 2015). "Moreover, all SPOP mutations identified in human prostate cancers disrupt the SPOP-AR interaction and abolish SPOP-induced AR degradation." (PMID 24508459, 2014). "Thus, it is possible that SPOP mutations augment AR functions in prostate cancer by inhibiting turnover of both AR and its coactivator SRC-3." (PMID 24508459, 2014). "Prostate-cancer-associated mutants of SPOP cannot bind to and promote AR destruction." (PMID 24508459, 2014). "The SPOP E3 ubiquitin ligase gene is frequently mutated in human prostate cancers." (PMID 24508459, 2014). "However, SPOP has a high mutation frequency in human tumor samples, with mutations occurring mainly in the MATH structural domain; these mutations cause inactivation of SPOP function, which leads to tumor progression, and SPOP mutations are more prevalent in prostate cancer and endometrial cancer." (PMID 41213915, 2025). "Thus, SPOP mutational status may serve as a prognostic marker for treating prostate cancer patients in a precision medicine manner." (PMID 39851497, 2025). "For example, mutations in SPOP, which occur early in the development of prostate cancer, are most appropriately modeled starting with normal luminal stem cells, which provide an appropriate context, as compared with prostate cancer cell lines, which contain several preexisting mutations." (PMID 37183816, 2023). "In detail, the loss-of-function mutations of SPOP could prevent ubiquitination-mediated PD-L1 degradation, demonstrating that patients with prostate cancer had a worse prognosis and therapy effect through increasing PD-L1 levels and decreasing tumor-infiltrating lymphocytes." (PMID 34838022, 2021). "Thus, prostate cancer-associated SPOP mutants fail to promote Geminin poly-ubiquitination." (PMID 34599168, 2021). "Endometrial cancer–associated SPOP mutations preferentially degrade BET proteins, while prostate-cancer–specific SPOP mutation results in impaired degradation of BET proteins, as mutations of SPOP degrons in BRD4 determine whether they bind BET proteins or not, thus influencing BET ubiquitination." (PMID 34540900, 2021). "Notably, prostate cancer-associated SPOP mutants are deficient in binding and promoting the degradation of substrates, leading to increased prostate cancer cell proliferation and invasion, indicating the loss of function of SPOP mutations and the tumor-suppressive role of SPOP in prostate cancer." (PMID 29996942, 2018). "Therefore, we speculated that prostate cancer-associated SPOP mutations may cause dysfunctions in regulating ATF2 protein levels." (PMID 29996942, 2018). "In addition, it is suggested that SPOP mutation might represent sensitivity to DNA damaging agents such as PARP inhibitor in prostate carcinoma." (PMID 29986747, 2018). "Here, we are the first to report that SPOP mutations are associated with dysregulation of mitochondrial dynamics in prostate cancer and this finding may have potential clinical implications in prostate cancer treatment." (PMID 28448495, 2017). "However, how SPOP mutations contribute to prostate cancer pathogenesis remains poorly understood." (PMID 28448495, 2017). "Also, AR transcriptional activity is increased in SPOP mutated prostate cancer." (PMID 29262542, 2017). "Therefore, our newly developed point-mutation-specific PRISM-SRM assays could be very useful to study the most commonly observed SPOP protein mutations in prostate cancer." (PMID 28810879, 2017).
prostate carcinoma (continued). "Interestingly, these mutants were exclusively localized as nuclear speckles in nearly 100% cells, implying that cytoplasmic retention ability of SPOP may be impaired by prostate cancer-associated mutations." (PMID 28448495, 2017). "Therefore, men that are diagnosed with types of prostate cancer in which the gene that encodes SPOP is mutated might benefit from treatment with PARP inhibitors or other therapies that affect DNA repair." (PMID 26374986, 2015). "In agreement with our finding that the SPOP-binding motif 645ASSTT649 is located in the hinge domain of the AR, we demonstrated that none of the hinge domain null AR variants could be bound by SPOP, thereby escaping SPOP-mediated protein degradation in prostate cancer cells." (PMID 24508459, 2014). "However, the pathophysiology of prevalent SPOP mutations in prostate cancer is poorly understood." (PMID 24508459, 2014). "Importantly, prostate-cancer-associated mutants of SPOP lose the capability to degrade SRC-3." (PMID 24508459, 2014). "GLI3 and AR appear to cooperate in promoting androgen-independent growth in SPOP-mutant prostate cancer cells." (PMID 40432836, 2025). "This accumulation contributes, in part, to SPOP inactivation-induced prostate cancer cell migration and invasion." (PMID 40771930, 2025). "The link between SPOP mutations and the stabilization of GLI3 provides insights into the genetic basis of prostate cancer." (PMID 40432836, 2025). "It has been demonstrated that SPOP acts as a tumor suppressor in prostate cancer by primarily targeting the pluripotency-maintaining transcription factor Nanog for polyubiquitination and subsequent degradation, thereby inhibiting prostate CSC traits." (PMID 40034124, 2025). "Histopathology images from The Cancer Genome Atlas (TCGA) prostate cancer data set, uterine corpus endometrial cancer data set, and our cohort revealed that SPOP-mutant tumors had larger nuclei compared with SPOP WT tumors." (PMID 40662365, 2025). "Studies have shown that ERK1/2 inhibits the Cullin 3/SPOP-mediated ubiquitination and degradation of PrLZ, regulating prostate cancer progression." (PMID 40764425, 2025). "SPOP mutations are predominantly clustered in the MATH domain, with specific hotspot residues such as F133 and F102 frequently mutated in prostate cancer." (PMID 40432836, 2025). "Recent studies have shown that SPOP plays vital roles in the tumorigenesis of various tumors, such as prostate cancer, renal cell carcinoma (RCC), and colorectal cancer." (PMID 41122967, 2025). "Efforts to exploit the dependence of SPOP-mutant prostate cancer cells on dysregulated AR signaling are ongoing, with small molecule inhibitors and gene-editing techniques being explored as potential therapeutic strategies." (PMID 40432836, 2025). "The discovery of SPOP mutations, particularly within the MATH domain, has unveiled a new layer of complexity in prostate cancer biology." (PMID 40432836, 2025). "Another E3 ligase, SPOP (Speckle-type POZ protein), inhibits migration and invasion of prostate cancer cells by directing proteasomal degradation of Nanog." (PMID 41385185, 2025). "In prostate cancer, SPOP acts as a tumor suppressor by facilitating the degradation of multiple oncogenic substrates." (PMID 41122967, 2025).
prostate carcinoma (continued). "We further generated 5 prostate cancer–associated SPOP mutants, and co-IP assays revealed that all 5 mutants showed impaired binding to LMNB2 compared with WT SPOP." (PMID 40662365, 2025). "Exploiting the dependence of SPOP-mutant prostate cancer cells on dysregulated AR signaling represents a promising therapeutic strategy." (PMID 40432836, 2025). "E3 ubiquitin ligase adaptor protein SPOP targets GLI3 for ubiquitin-mediated proteasomal degradation in prostate cancer cells." (PMID 40432836, 2025). "Speckle-type pox virus and zinc finger protein (SPOP) has emerged as a key focus in prostate cancer research due to its critical role in regulating the androgen receptor (AR) signaling pathway." (PMID 40432836, 2025). "Emerging evidence suggests that SPOP functions as a double-edged sword: acting as a tumor suppressor in prostate cancer (PCa), hepatocellular carcinoma (HCC), and colorectal cancer (CRC), while potentially serving as an oncoprotein in kidney cancer (KC)." (PMID 40521202, 2025). "In this study, we systematically analyze the effects of SPOP mutants derived from prostate cancers and endometrial cancers on IRF2BP2 and find the differential outcomes." (PMID 38409107, 2024). "NEO2734 has been shown to be an effective therapeutic intervention for SPOP-mutant prostate cancer in preclinical studies." (PMID 38201308, 2024). "TRIM24 plays a crucial role in promoting cell proliferation in SPOP-mutant prostate cancer cells, particularly under conditions of low androgen availability." (PMID 39160596, 2024). "Prostate cancer organoids retain parental genetic features, including TMPRSS2–ERG fusion, SPOP mutation, SPINK1 overexpression, and CHD1 loss." (PMID 39309690, 2024). "Speckle-type POZ (SPOP) is described as an essential tumor suppressor factor in gastric cancer, colorectal cancer, and prostate cancer (PCa)." (PMID 39630373, 2024). "Studies have shown that Asian populations exhibit higher mutation rates of SPOP and FOXA1 in prostate cancer, while European populations are more characterized by ERG fusion mutations and PTEN loss." (PMID 39882449, 2024). "Speckle-type POZ protein (SPOP), another tumor suppressor, is frequently mutated in solid tumors, including breast, colon, gastric, kidney, and prostate cancers." (PMID 39253293, 2024). "ATR inhibition can also inflame the TME in the absence of DNA-damaging agents, such as through the direct activation of a CDK1 axis, leading to SPOP-dependent PDL1 degradation in prostate cancer cell lines." (PMID 38473997, 2024). "A noteworthy finding within this molecular classification is the significantly higher prevalence of IDC-P in prostate cancers within the molecular class characterized by SPOP mutant cancers, accounting for up to 90% of cases within this group." (PMID 38067216, 2023). "In prostate cancer, BRD4 and MYC are direct substrates of SPOP, and the stabilization of BRD4 is directly linked to BETi resistance in prostate cancer cells carrying SPOP mutations." (PMID 37036970, 2023). "In recent years, G3BP1 has been reported to promote the development of prostate cancer by inhibiting the degradation of AR through inhibiting SPOP." (PMID 37904149, 2023). "In prostate cancer, mutated Speckle type POZ protein (SPOP) leads to impaired degradation and upregulation of BRD4 protein which confers intrinsic resistance to BET inhibitors." (PMID 36733715, 2023). "Given that co-occurrence of SPOP mutations and CHD1 deletion define a distinct molecular subtype of prostate cancer, further studies are needed to assess if they have synergistic effects in response to DNA-damaging therapies." (PMID 36776288, 2023). "Blockage of TGF-β/SMAD cascade signaling boosted SPOP expression and inhibited prostate cancer cell stemness." (PMID 36769824, 2023).